GLYR1 (glyoxylate reductase 1 homolog)
Description:
Cytokine-like nuclear factor with chromatin gene reader activity involved in chromatin modification and regulation of gene expression. Acts as a nucleosome-destabilizing factor that is recruited to genes during transcriptional activation. Recognizes and binds histone H3 without a preference for specific epigenetic markers and also binds DNA. Interacts with KDM1B and promotes its histone demethylase activity by facilitating the capture of H3 tails, they form a multifunctional enzyme complex that modifies transcribed chromatin and facilitates Pol II transcription through nucleosomes. Stimulates the acetylation of 'Lys-56' of nucleosomal histone H3 (H3K56ac) by EP300. With GATA4, co-binds a defined set of heart development genes and coregulates their expression during cardiomyocyte differentiation. Regulates p38 MAP kinase activity by mediating stress activation of MAPK14/p38alpha and specifically regulating MAPK14 signaling. Indirectly promotes phosphorylation of MAPK14 and activation of ATF2. The phosphorylation of MAPK14 requires upstream activity of MAP2K4 and MAP2K6.
Synonyms: NPAC; hNDF; HIBDL; NP60; BM045; N-PAC
Tractability: Small molecule: a structure with a bound ligand is known; it has a binding pocket of medium quality. PROTAC: UniProt records ubiquitination sites on it; ubiquitination databases record sites on it; its protein half-life has been measured.
Gene: Protein-coding gene on chromosome 16 (4,803,202 to 4,847,343, reverse strand). Ensembl gene ENSG00000140632.
Subcellular location: Nucleus; Chromosome
Subcellular location (Human Protein Atlas): Nucleoplasm; Cytosol
Gene Ontology:
Molecular function: chromatin binding; chromatin-protein adaptor activity; DNA binding; histone binding; nucleosome binding; protein binding; NAD binding; NADP binding
Biological process: transcription elongation-coupled chromatin remodeling; transcription initiation-coupled chromatin remodeling
Cellular component: chromatin; chromosome; nucleoplasm; nucleosome; nucleus
Genetic constraint (gnomAD): Loss-of-function variants: 19 observed, 70.16 expected, observed/expected ratio (o/e) 0.27, 90% interval 0.19 to 0.4. The synonymous counts are far from expectation, so gnomAD's model fits this gene poorly and the ratio says little. Missense variants: 563 observed, 693.11 expected, observed/expected ratio (o/e) 0.81, 90% interval 0.76 to 0.87. Synonymous variants: 374 observed, 265.69 expected, observed/expected ratio (o/e) 1.41, 90% interval 1.29 to 1.53.
Homologues: Orthologues: chimpanzee GLYR1 (100% identical), macaque GLYR1 (99% identical), dog GLYR1 (99% identical), guinea pig GLYR1 (99% identical), pig GLYR1 (99% identical), mouse Glyr1 (99% identical), rat Glyr1 (92% identical), tropical clawed frog glyr1 (80% identical), zebrafish glyr1 (69% identical), Drosophila melanogaster Ndf (34% identical). Paralogues in human: HIBADH (16% identical).
Diseases named in the same sentence as GLYR1 in open-access papers:
GLYR1 is named in the same sentence as 12 diseases in open-access papers, as found by Europe PMC text mining. Sharing a sentence is not in itself a finding about the gene and the disease. The quoted sentences say what the papers report.
colorectal cancer (3 papers, 2020 to 2025). A primary or metastatic malignant neoplasm that affects the colon or rectum. "GLYR1 has a high mutation frequency in microsatellite instability colorectal cancer (MSI CRC) and is presumed to be a novel tumor suppressor." (PMID 32370786, 2020). "GLYR1, the favorable protein for HGSC (DSS), is a transcription regulator having shown favorable prognosis in colorectal cancer." (PMID 40778374, 2025).
colon cancer (2 papers, 2023 to 2025). "The most specific loci were in the exons of genes JAK1 and CHD3 (for endometrial cancer); BMPR2, ELAV3, GLYR1, and ZNF43 (for colon cancer); and XYLT2 (for stomach cancer)." (PMID 37894432, 2023).
retinitis pigmentosa (1 paper, 2021). Retinitis pigmentosa (RP) is an inherited retinal dystrophy leading to progressive loss of the photoreceptors and retinal pigment epithelium and resulting in blindness usually after several decades. "Strikingly, eight of the 67 exclusive candidates are associated with retinitis pigmentosa (human orthologues in parentheses): Gnat1 (GNAT1), Rom1a and Rom1b (ROM1), Kfharr-r2 (SAG, ARRESTIN, RP47), Rgra (RGR, RP44), Tbl2 (TBL2), Sec31b (SEC31B) and Glyr1 (GLYR1)." (PMID 34106226, 2021).
cancer (2 papers, 2017 to 2023). A tumor composed of atypical neoplastic, often pleomorphic cells that invade other tissues. "GLYR1 activity was elevated in RB1 mutant cancers and taking GLYR1 activity into account abolished the negative statistical relationship between RB1 mutation and NNMT expression." (PMID 37883365, 2023).
tumor (2 papers, 2020 to 2023). "Previous studies have revealed that GLYR1 expression levels correlate positively with tumor differentiation." (PMID 32370786, 2020). "Accelerated cell cycle progression is known to be a common feature of tumor cell proliferation; therefore, we also analyzed the effect of GLYR1 downregulation on CRC cell proliferation in vitro by colony formation and CCK-8 assays." (PMID 32370786, 2020). "GLYR1 has a high mutation frequency (51%) in MSI CRC, and has been implicated as a tumor suppressor; however, the role of GLYR1 in tumors is still unclear." (PMID 32370786, 2020). "Prompted by this, we examined the TCGA human primary tumour dataset to test whether GLYR1 might be involved in regulating NNMT in human cells." (PMID 37883365, 2023). "The results indicated that GLYR1 expression was closely related to tumor position (ρ = − 0.245, P = 0.001), tumor size (ρ = 0.216, P = 0.004), tumor grade (ρ = 0.319, P < 0.001), mucinous component (ρ = − 0.235, P = 0.007) and microsatellite instability (ρ = − 0.641, P < 0.001)." (PMID 32370786, 2020). "To investigate the relationship between GLYR1 and MSI, we analyzed the correlation between GLYR1 and MRR genes using the R2 database [Tumor Colon MSI-status (Core-Transcript) - Sveen - 95 - rma-sketch - huex10t]." (PMID 32370786, 2020). "GLYR1 was significantly downregulated in MSI CRC and its expression was negatively correlated with tumor size and positively correlated with tumor differentiation in CRC patients." (PMID 32370786, 2020). "From these experiments, the transcriptional regulator GLYR1 emerged as a potential link between the SAM/SAH ratio and NNMT expression, as we showed GLYR1 likely mediates the relationship between HMT levels and NNMT expression in human primary tumours." (PMID 37883365, 2023).
GLYR1 also shares sentences with these, for which no sentence is quoted: adenocarcinoma (1 paper); encephalitis (1); endometrial cancer (1); lung adenocarcinoma (1); prostate tumors (1); squamous cell carcinoma (1); stomach cancer (1).